MIR4289 (microRNA 4289)
Synonyms: hsa-mir-4289
Gene: MicroRNA gene on chromosome 9 (88,745,836 to 88,745,905, reverse strand). Ensembl gene ENSG00000265873.
Homologues: Orthologues: chimpanzee MIR4289 (100% identical).